C7orf78 (chromosome 7 open reading frame 78)
Gene: Protein-coding gene on chromosome 7 (12,469,621 to 12,542,222, forward strand). Ensembl gene ENSG00000226690.
Homologues: Orthologues: chimpanzee C7orf78 (97% identical), macaque C7orf78 (93% identical), pig C7orf78 (70% identical), dog C7orf78 (62% identical).